IL17A (interleukin 17A)
Diseases named in the same sentence as IL17A in open-access papers (continued):
Sharing a sentence is not in itself a finding about the gene and the disease.
autoimmune disease (continued). "Moreover, IL17A and IL22 are also known to mediate type 3 immunity and disruption in their function has been associated with various infectious diseases, autoimmune disorders, and cancer." (PMID 38993777, 2024). "Interleukin-17A (IL-17A) is a key inflammatory cytokine in several autoimmune diseases." (PMID 36857006, 2023). "However, if dysregulated, IL-17A responses can promote the development and chronicity of inflammatory disorders in a number of autoimmune diseases." (PMID 38202170, 2023). "Furthermore, the overproduction of IgE and IL‐17A is also an important pathogenesis of autoimmune diseases." (PMID 37249293, 2023). "The IL-17A-expressing CD4 T cells are a key mediator of autoimmune diseases." (PMID 37175691, 2023). "IL-17A and IL-17A-producing T cells are important mediators of various autoimmune disorders." (PMID 37152368, 2023). "IL-17RC is critical to signal transduction via IL-17A and the pathogenesis of autoimmune diseases." (PMID 37894114, 2023). "IL-17A has received much attention for its pro-inflammatory role in autoimmune disease, but accumulating evidence indicates that IL-17A has important context- and tissue-dependent roles in maintaining health during response to injury, physiological stress, and infection." (PMID 38068860, 2023). "Interleukin-17A plays a crucial role in multiple sclerosis and other autoimmune diseases." (PMID 36857006, 2023). "IL-17A is a marker of the T-helper cell 17 subpopulation, which protects the host from extracellular pathogens and participates in inflammatory responses in autoimmune diseases." (PMID 35372072, 2022). "Accumulating evidence now underscores an integral role of IL-17A in driving the pathophysiology and clinical manifestations in three potentially life-threatening autoimmune diseases, namely, systemic lupus erythematosus, Sjögren's syndrome, and systemic sclerosis." (PMID 35620115, 2022). "IL-17A and IL-17F are currently drug targets for the treatment of autoimmune diseases." (PMID 36355537, 2022). "This review reports on the synergistic interactions of IL-17A with other critical determinants such as B cells, neutrophils, stromal cells, and the vasculature that promote the characteristic immunopathology of these autoimmune diseases." (PMID 35620115, 2022). "It is possible that IFN-γ+ and IL-17A+ γδ T cells share some common features with other human infections and autoimmune diseases in skin, and further investigation is necessary to prove this hypothesis." (PMID 36389696, 2022). "Thus, GLK is a promising therapeutic target by both blocking IL-17A-mediated autoimmune diseases 10 and enhancing Treg-mediated immune suppression." (PMID 35966593, 2022). "Up to 8-fold higher levels of IL-17A and 5-fold higher levels of IL-22 are seen in the serum of patients with autoimmune diseases such as rheumatoid arthritis, while a 3-fold increase in serum levels of IL-23 has been reported in patients with multiple sclerosis." (PMID 34203644, 2021). "IL-17A, secreted by Th17 cells, was found upregulated in human inflammatory and autoimmune disease." (PMID 35046930, 2021). "In the present study, we hypothesized that increases in IL-27 and SOCS3 and a decrease in IL-17A in T. gondii–infected mouse brains would inhibit the progression of autoimmune diseases like EAE." (PMID 33205383, 2021). "However when the release of IL-17A is exacerbated, this can also lead to the destructive tissue pathologies of inflammatory and autoimmune diseases." (PMID 35003055, 2021). "Therefore, placental explants were treated with a clinically relevant combination of IL-17A, IL-22, and IL-23, at concentrations seen in patients with autoimmune diseases." (PMID 34203644, 2021). "Several studies have shown that IL-17A+IFNΥ+ T cells were elevated in various autoimmune diseases." (PMID 34040613, 2021). "The role of IL-17A in many autoimmune diseases is now well-known." (PMID 34054854, 2021).
autoimmune disease (continued). "Finally, we identified an antigenic α-synuclein epitope that promoted expression of IL17A, a pro-inflammatory cytokine involved in autoimmune diseases." (PMID 34648304, 2021). "Interleukin 17A (IL-17A) is a naturally occurring cytokine that links T-cell activation to neutrophil mobilization and activation, and is one of the principal pro-inflammatory cytokines in some autoimmune diseases." (PMID 35310892, 2021). "IL-17A has a crucial role in intestinal immunity, autoimmune disease and host defense." (PMID 32391010, 2020). "IL-17A has been demonstrated to be essential for the development of various autoimmune diseases." (PMID 32742600, 2020). "IL-17A is crucial for host protective immunity against various microbial pathogens, whereas Th17 cells expressing IL-17A are emerging as critical mediators of autoimmune diseases, thus increasing interest and research into the development of strategies to treat these autoimmune diseases." (PMID 33175869, 2020). "Neutrophils are a source of IL-17a in the setting of inflammation and autoimmune diseases." (PMID 30616627, 2019). "Furthermore, treatment of GLK inhibitor reduces disease severity of mouse autoimmune disease models and decreases IL-17A production of human autoimmune T cells." (PMID 31640697, 2019). "As IL-17C has been reported promote the production of IL-17A by Th17 lymphocytes in inflammatory conditions (such as autoimmune disease), the authors concluded that these effects may be due more to the promotion of IL-17A than to IL-17C alone." (PMID 31507598, 2019). "However, IL-23 signaling through the IL-23 receptor (IL-23R) increases IL-17A production and is important in pathogenesis of autoimmune diseases and potentially asthma." (PMID 31849948, 2019). "Former researchers have established that IL-17A, which is a pro-inflammatory cytokine in autoimmune diseases, could also participates in tumor development." (PMID 31159823, 2019). "The cytokine IL-17A plays critical roles in the pathogenesis of autoimmune diseases." (PMID 31318609, 2019). "With this case report, we hope to raise physician awareness of the possible autoimmune disorders that may arise subsequent to novel immunomodulation therapies, particularly that RP may develop subsequent to inhibition of IL-17A." (PMID 30057845, 2018). "Here we demonstrated an important novel role for RFX1 in the regulation of the increased IL-17A expression in CD4+ T cells of patients with SLE, as well as in the differentiation of Th17 cells and the development of the IL-17-related autoimmune diseases EAE and lupus in mice." (PMID 29422534, 2018). "Our findings suggest that inhibitors of GLK or the AhR-RORγt complex could be used as IL-17A–blocking agents for IL-17A–mediated autoimmune diseases." (PMID 30214937, 2018). "Unlike CD4+CD25+Foxp3+ Tregs, which dominate hematological system tumors and autoimmune diseases, γδ T cells play a key role in the pathological progress of AMI and it may be associated with the IL-17A mediated pathway, but the specific mechanism is unknown." (PMID 29976209, 2018). "Both IL-17A and Th17 cells are highly involved in the pathogenesis of several autoimmune diseases, including rheumatoid arthritis (RA), while playing a significant role in autoimmune disorders mediated by excessive inflammation." (PMID 29326694, 2017). "IL-17 has been designated IL-17A to indicate that it is the founding member of the IL-17 cytokine family consisting of IL-17A-F members playing an active role in inflammatory responses and in autoimmune diseases." (PMID 28114998, 2017). "Th17 cells functioned to induce inflammation and autoimmune diseases by producing IL-17A." (PMID 27069316, 2016). "IL-17A and IL-17F are the most intensively studied due to their role in both protective immunity against Candida albicans and their capacity to promote inflammation in autoimmune diseases such as rheumatoid arthritis and psoriasis." (PMID 31557985, 2016).
autoimmune disease (continued). "Th17 cells that make IL-17A/ IL-17F, IL-22, IL-21 etc. are highly inflammatory and have been shown to activate osteoclasts that lead to bone destruction in RA and are also involved in other autoimmune disorders." (PMID 27486885, 2016). "Taken together, all these results support the hypothesis that IL-17A plays a crucial role in the development of chronic inflammation and probably in the hemostatic disorders observed in patients with autoimmune diseases." (PMID 27561214, 2016). "Taken together, these results suggest that Gβγ may prove to be an attractive drug target for the many autoimmune diseases associated with increased levels of IFN-γ and IL-17A." (PMID 27095999, 2015). "Although Th17 cells play a critical biological function in clearing extracellular pathogens, the inappropriate production of IL-17A by these cells is thought to be involved in the pathogenesis of various inflammatory, autoimmune diseases and transplant rejection in humans." (PMID 26325187, 2015). "Both IL-17A and IL-17F are reported to be involved in multiple human autoimmune diseases, but their functions and potency may vary." (PMID 26325187, 2015). "Interleukin-17A (IL-17A), the most widely studied member of the IL-17 cytokine family, is a cytokine which emerged to be critical for host defense as well as in the pathogenesis of autoimmune disorders." (PMID 24940514, 2014). "Th17 cells secrete IL-17A and participate in the pathogenesis of many autoimmune diseases." (PMID 23874630, 2013). "IL-17A is a well-known pro-inflammatory cytokine involved in autoimmune diseases." (PMID 23837842, 2013). "The corollary to this is that efficacy of a vaccine that relies heavily on IL-17A to confer protective immunity may be compromised in patients treated with IL-17A targeted drugs, which are in late stage clinical development for autoimmune diseases." (PMID 23592988, 2013). "Interleukin (IL)-17A plays an important role in host defense against a variety of pathogens and may also contribute to the pathogenesis of autoimmune diseases." (PMID 22768117, 2012). "In this particular context, the stimulation of Th17 cells might be beneficial for clearance of different infectious agents, but IL-17A was also reported to be involved in the pathogenesis of autoimmune diseases." (PMID 22291945, 2012). "TH17 effector cells secrete at least one of the six cytokines belonging to the IL-17 family, that is, IL-17A, IL-17B, IL-17C, IL-17D, IL-25 and/or IL-17F; however, IL-17A, the signature cytokine, has received the greatest attention in studies of autoimmune diseases." (PMID 21182786, 2010). "Interleukin-17A (IL-17A) is the founding member of a novel family of inflammatory cytokines that plays a critical role in the pathogenesis of many autoimmune diseases, including multiple sclerosis (MS) and its animal model, experimental autoimmune encephalomyelitis (EAE)." (PMID 19400960, 2009). "However, elevated IL-17A in several autoimmune diseases including MS/EAE contributes to disease pathogenesis." (PMID 19400960, 2009). "In addition, IL-17A is centrally involved in several autoimmune diseases." (PMID 41750609, 2026). "In light of the pathological significance of IL-17A in autoimmune diseases and its therapeutic value as a drug target, an alternative approach to clear IL-17A may complement monoclonal antibody drugs that facing challenges in immunogenicity and the resulted anti-drug antibodies." (PMID 38396109, 2024). "These discoveries open a new therapeutic possibility for various inflammatory and autoimmune diseases, such as multiple sclerosis, rheumatoid arthritis, Crohn’s disease, and autoimmune uveitis; increased IL-24 expression in addition to IL-17A could be a possible therapeutic strategy." (PMID 37444474, 2023).
autoimmune disease (continued). "In addition, this review reports on the synergistic interactions of IL-17A with other critical determinants such as B cells, neutrophils, stromal cells, and the vasculature that promote the characteristic immunopathology of these autoimmune diseases." (PMID 35620115, 2022). "Likewise, the safety of IL-17A inhibitors was controversial in other autoimmune diseases." (PMID 33432451, 2021). "Thus, modulation of the RORγt/IL-17A axis may represent an attractive therapeutic target for the treatment of autoimmune disorders and some cancers." (PMID 34752458, 2021). "Thus, understanding the mechanisms controlling IL-17A induction in SLE may lead to the discovery of novel therapeutic targets for SLE or maybe other autoimmune diseases." (PMID 31318609, 2019). "Having observed that EBV DNA enhances IL-17A production in the murine system, we intended to examine whether similar effects for this viral DNA can be detected in humans in particular within the setting of an autoimmune disease." (PMID 29995930, 2018). "Thus, understanding the mechanism(s) controlling IL-17A transcription may lead to the discovery of novel therapeutic targets for autoimmune diseases." (PMID 30214937, 2018). "Th17 cells, named for their signature production of IL-17A, also secrete IL-17F, IL-21, and IL-22, thereby inducing an enormous tissue reaction due to the broad distribution of the IL-17 and IL-21 receptors and exerting a crucial role in the development of inflammatory and autoimmune diseases." (PMID 27176825, 2016). "Secretion of the proinflammatory cytokine Interleukin-17A (IL-17A) is the hallmark of a unique lineage of CD4 T cells designated Th17 cells, which may play a crucial role in the pathogenesis of rheumatoid arthritis (RA) and many autoimmune diseases." (PMID 24340045, 2013). "Since its first description in 1993, IL-17A (also referred to as IL-17) has received much attention as an important proinflammatory cytokine with a critical role in immune defence against extracellular pathogens as well as in the pathogenesis of different autoimmune diseases." (PMID 24340045, 2013). "While this T cell lineage is beneficial for defense against certain extracellular bacterial and fungal infections, the secretion of IL-17A and IL-17F by Th17 cells may contribute to autoimmune disease pathogenesis by promoting the accumulation of neutrophils within tissues." (PMID 23505568, 2013). "miR-155 potentiates the development of both regulatory T cells (Treg) and T helper 17 (Th17) cell subsets while augmenting IL-17A secretion through SOCS1 targeting, thereby influencing immune tolerance and autoimmune diseases." (PMID 40282426, 2025). "Firstly, we detected IL-2, IL-4, IL-5, IL-13, IL-17A, IL-17F, IL-22, IFN-γ, and TNF-α in the plasma to exclude the influence of infection or autoimmune disorders, and the standard curves were verified." (PMID 38343544, 2024). "IL-17A, TCR+ γδ T cells, and CD5+ В1 cells play a crucial role in preventing pneumococcal infection, but can also contribute to autoimmune diseases." (PMID 38840926, 2024). "In various inflammatory and autoimmune disorders, a novel type of IFN gamma/IL-17A–double-positive T cells has recently been described." (PMID 37256725, 2023). "Of interest, dual IL-17A–positive and IFN gamma–positive T cells have been reported in various fibrosing autoimmune diseases." (PMID 37256725, 2023). "An increasing number of studies have revealed the clinical relevance of Th17/Th1 cells and IL-17A and IFN-γ in patients with immune diseases such as autoimmune diseases and many other intestinal immune diseases." (PMID 38090557, 2023). "T helper 17 (Th17) cells, a novel subset of CD4+ T cells, are known to secrete IL-17A, IL-17F, IL-22, GM-CSF, and IFN-γ, which are involved in inflammation, autoimmune diseases, and graft-versus-host disease (GVHD)." (PMID 37063881, 2023).
autoimmune disease (continued). "Thus, further studies are needed to explore the role of IL-17A in atherosclerosis to evaluate a potential therapeutic strategy targeting IL-17, even though IL-17A is involved in host defense against bacterial infections at the mucosa and involved in autoimmunity diseases." (PMID 36133421, 2022). "Il-17A, together with IL-23 through their proinflammatory action, plays an important role in mediating intestinal inflammation in IBA and also in other autoimmune diseases." (PMID 35678656, 2022). "The IL-17 family includes pro-inflammatory cytokines of whom IL-17A is a marker of a specific CD4+ T cell subset named CD4+ T helper 17 (Th17) and is involved in autoimmune diseases as well as infections." (PMID 36613822, 2022). "IL-17A producing cells including Th17 cells (IL-17A producing CD4+ T helper cells) are involved in human cancers and autoimmune diseases." (PMID 35902909, 2022). "IL-17A is produced predominantly by CD4+ Th17 cells in response to cytokine IL-23 and plays an important role in various autoimmune diseases, including uveitis." (PMID 34356895, 2021). "MicroRNA 155 was found to be high expressed in autoimmune disease and was positively correlated with PASI and IL-17A level in psoriatic patients." (PMID 33981308, 2021). "To evaluate the therapeutic effects of the IL-17A DNA vaccine, we selected female NZBWF1 mice, which spontaneously develop an autoimmune disease closely resembling human SLE." (PMID 32059488, 2020). "Two central CD4+ Th subsets that play a central role in adaptive autoimmune disease are Th1 cells that secrete IFN-γ and Th17 cells that secrete IL-17A, IL-17F, and IL-17A/F as their signature cytokines." (PMID 30653583, 2019). "In addition, verteporfin may be a potential treatment for IL-17A–mediated autoimmune disease." (PMID 31318609, 2019). "Due to the relevance of IL-17A in the pathophysiology of several inflammatory and autoimmune diseases, we characterized the mechanisms and signaling mediators responsible for CD28-induced IL-17A expression." (PMID 31068940, 2019). "T helper 17 cells [TH17, interleukin-17A (IL-17A)–producing CD4+ T cells] and IL-17A play critical roles in the pathogenesis of autoimmune diseases." (PMID 30214937, 2018). "Vγ4 T cells, as the major γδ T cells in the dermis, are capable of secreting IL-17A and IFN-γ, which play distinctive roles in autoimmune diseases, graft rejection, antiviral immunity, and antitumor responses." (PMID 29915573, 2018). "IL-17A originates from various immune cells, such as Th17, Tfh17, and CD8+T cells, which contribute to tissue damage in GD and other autoimmune diseases." (PMID 30956992, 2018). "Interleukin-17A (IL-17A) is a pro-inflammatory cytokine produced by TH17 cells that participates and contributes in host defense and autoimmune disease." (PMID 30728820, 2018). "Th17 cells, a key player in autoimmune diseases and antibiosis, are differentiated from naïve T cells (CD4+) stimulated by IL-6, TGF-β, IL-1β, IL-21 and IL-23 and release IL-17A, IL-17F, IL-21 and IL-22." (PMID 28899359, 2017). "Recent studies showed that γδT cells play an important role in aseptic inflammation and autoimmune diseases in an IL17A-dependent manner; particularly, IL-17A-producing γδ T cells contribute to the acute live injury induced by Acetaminophen11." (PMID 28377603, 2017). "In autoimmune diseases, MAIT cells can maintain the integrity of the intestinal epithelial barrier by secreting interleukin (IL)‐22 and can also transform into a major source of the proinflammatory factor IL‐17A under pathological conditions." (PMID 41179703, 2025). "IL-17A inhibits the Th17 cytokine program via negative feedback regulation through autocrine induction of IL-24, preventing the Th17 pathogenicity in autoimmune diseases." (PMID 37444474, 2023).